ALK (ALK receptor tyrosine kinase)
Diseases named in the same sentence as ALK in open-access papers (continued):
Sharing a sentence is not in itself a finding about the gene and the disease.
anaplastic large cell lymphoma (continued). "Chosen cell lines represent different subgroups of mTCL, in particular ALK+ anaplastic large cell lymphoma (ALCL), ALK− ALCL, PTCL not otherwise specified (PTCL‐NOS), hepatosplenic T‐cell lymphoma (HSTCL), cutaneous T‐cell lymphoma (CTCL) and natural‐killer/T‐cell lymphoma (NKTCL)." (PMID 40165380, 2025). "The most commonly observed subtypes are the so-called PTCL not otherwise specified (PTCL NOS), the T-follicular helper-related PTCL, angioimmunoblastic type (AITL) and the anaplastic large cell lymphomas (ALCL), and anaplastic kinase-negative (ALK−) or positive (ALK+)." (PMID 39409979, 2024). "Anaplastic lymphoma kinase (ALK) is a receptor tyrosine kinase that is aberrantly expressed in several human cancers, including an aggressive subtype of T-cell lymphoma known as ALK-expressing anaplastic large cell lymphoma (ALK+ ALCL), NSCLC and neuroblastoma." (PMID 39456995, 2024). "Case LYWS-1418 from J Coviello was a case of CD30+ large cell lymphoma with features of ALK-negative anaplastic large cell lymphoma (ALCL) and possible PAX5 expression in rare CD30+ tumor cells, raising the differential diagnosis of CHL with expression of T-cell markers." (PMID 37646869, 2023). "However, it is of note that aberrant expression of PAX5 has been reported in ALK-negative anaplastic large cell lymphoma (ALCL), secondary to extra copies of the PAX5 gene." (PMID 35159009, 2022). "In 2016, the World Health Organization (WHO) classified anaplastic large cell lymphoma into four categories: ALK-positive ALCL (ALK+ALCL), ALK-negative ALCL (ALK−ALCL), primary cutaneous ALCL (pcALCL), and breast-implant-associated ALCL (BIA-ALCL), respectively." (PMID 35406421, 2022). "In anaplastic large cell lymphomas (ALCL), TARC is expressed in around half of the anaplastic lymphoma kinase (ALK)-negative ALCL and in none of the ALK-positive ALCL." (PMID 33672548, 2021). "For example, PD-L1 expression is commonly (>50% of cases) seen in peripheral T-cell lymphomas (PTCL) such as NK/T-cell lymphoma (NKTCL), angioimmunoblastic T-cell lymphoma (AITL), and anaplastic lymphoma kinase (ALK)-negative anaplastic large cell lymphoma (ALCL)." (PMID 33804869, 2021). "In anaplastic large cell lymphomas, all three ALK-positive cases were positive (scoring 2, 3, or 4) for IDO and both ALK-negative cases were negative for IDO." (PMID 32370297, 2020). "PD-L1 is upregulated in anaplastic large cell lymphoma (ALCL), and novel mechanisms of PD-L1 regulation and expression have been discovered in anaplastic lymphoma kinase- (ALK-) positive and ALK-negative subtypes of the disease." (PMID 33178841, 2020). "Around 8–10% of sporadic NB tumours present with point mutations in the kinase domain of the full-length ALK receptor; this is in contrast to the oncogenic NPM-ALK and EML4-ALK fusions that drive ALK-positive anaplastic large cell lymphoma (ALCL) and non-small cell lung cancer (NSCLC), respectively." (PMID 31088252, 2019). "Systemic anaplastic large cell lymphomas (ALCL) are a category of T-cell non-Hodgkin’s lymphomas which can be divided into anaplastic lymphoma kinase (ALK) positive and ALK negative subgroups, based on ALK gene rearrangements." (PMID 29346274, 2018). "Anaplastic large-cell lymphoma (ALCL) accounts for 12% of T-NHL cases, of which 6.5% are anaplastic lymphoma kinase (ALK) positive and 5.5% are ALK negative." (PMID 30231561, 2018). "Anaplastic large cell lymphomas (ALCL) represent a peripheral T-cell lymphoma subgroup, stratified based on the presence or absence of anaplastic lymphoma kinase (ALK) chimeras." (PMID 27793034, 2016). "The rarer form of ALK –ve large cell lymphoma also has clonally rearranged T cell receptor VDJ genes and similarly to ALK + ve large cell lymphoma does not have cell surface T cell receptors." (PMID 25605631, 2015).
anaplastic large cell lymphoma (continued). "T-cell lineage lymphoma with an intense membranous and paranuclear CD30 expression in the absence of ALK1 raises a differential diagnosis of peripheral T-cell lymphoma (PTCL), NOS and anaplastic large cell lymphoma (ALCL), ALK negative." (PMID 25143841, 2014). "A nodular area in the breast specimen showed ALK negative anaplastic large cell lymphoma (ALCL)." (PMID 25734041, 2012). "In addition, despite the fact that anaplastic large cell lymphoma is not classified as an HIV-related lymphoma by the WHO, at least 20 instances have been recorded, with rare incidences of ALK expression." (PMID 35406421, 2022). "PTCL is classified into subtypes such as angioimmunoblastic T-cell lymphoma (AITL), ALK-positive anaplastic large-cell lymphoma (ALK+ALCL), ALK-negative anaplastic large-cell lymphoma (ALK-ALCL), peripheral T-cell lymphoma not otherwise specified (PTCL-NOS), and so on." (PMID 36465366, 2022). "Like ALK, EMA is more often present in systemic anaplastic large-cell lymphoma with secondary skin involvement rather than in primary cutaneous anaplastic large-cell lymphoma (67% versus 32%, respectively), so EMA expression cannot be used reliably to stage cutaneous anaplastic large-cell lymphoma." (PMID 16623775, 2006). "Furthermore, genetic drivers will be discussed for ALK-negative anaplastic large cell lymphomas and their role in differentiating these from CD30+ peripheral T-Cell lymphoma, not otherwise specified (NOS) and primary cutaneous anaplastic large cell lymphoma." (PMID 35330161, 2022). "However, rearrangement of ALK is not restricted only to ALK-RCC, but has also been previously documented in other non-renal tumors, such as non-small-cell lung adenocarcinoma, anaplastic thyroid carcinoma, anaplastic large-cell lymphoma, and others." (PMID 31936678, 2020). "A skin biopsy was obtained and was consistent with an anaplastic lymphoma kinase (ALK)-negative, CD4+ CD30+, PD-1−, primary cutaneous anaplastic large cell lymphoma (ALCL)." (PMID 30454071, 2018). "According to the 2016 World Health Organization (WHO) classification, nodal T-cell lymphomas include anaplastic lymphoma kinase (ALK)-positive and ALK-negative anaplastic large cell lymphoma (ALCL), angioimmunoblastic T-cell lymphoma (AITL), and PTCL not otherwise specified (PTCL-NOS)." (PMID 40839148, 2025). "Of them, the most common histological subtypes were PTCL-NOS (n = 28 [31.5%]), ENKTL (n = 19 [21.3%]), anaplastic lymphoma kinase-negative anaplastic large cell lymphoma (ALCL ALK-, n = 13 [14.6%]) and anaplastic lymphoma kinase-positive anaplastic large cell lymphoma (ALCL ALK+, n = 7 [7.9%])." (PMID 33436023, 2021). "Anaplastic lymphoma kinase (ALK), discovered in 1994, is a transmembrane receptor tyrosine kinase that have been identified in several types of cancer, including anaplastic large cell lymphoma(ALCL), inflammatory myofibroblastic tumor, and non-small-cell lung cancer(NSCLC)." (PMID 35280798, 2022).
lung adenocarcinoma (738 papers, 2008 to 2026). A carcinoma that arises from the lung and is characterized by the presence of malignant glandular epithelial cells. "Univariate analysis of the effects of EGFR gene mutation and ALK gene mutation on pathological features of invasive lung adenocarcinoma." (PMID 41378298, 2025). "In this study, we quantitatively evaluated the use of intratumoral and peritumoral radiomics using preoperative CT images in predicting ALK mutation in patients with lung adenocarcinoma." (PMID 40083024, 2025). "The ALK gene is also commonly mutated in lung adenocarcinoma, with a mutation rate of approximately 3%–7%." (PMID 41020204, 2025). "This study aimed to investigate CAF-driven molecular networks that shape the therapeutic susceptibility of ALK-driven lung adenocarcinoma cells." (PMID 40524253, 2025). "This study found a correlation between EGFR mutation status, ALK positivity, and demographic, tumor, radiological, and pathological features in lung adenocarcinoma patients." (PMID 41378298, 2025). "The EML4/ALK fusion gene has been extensively studied in lung adenocarcinoma and squamous cell carcinoma and is associated with metastasis." (PMID 40486961, 2025). "Non-small cell lung cancer (NSCLC), particularly lung adenocarcinoma, is predominantly driven by mutations in driver genes, primarily including anaplastic lymphoma kinase (ALK) rearrangements and epidermal growth factor receptor (EGFR) mutations." (PMID 40052122, 2025). "We developed a combined model including clinical TNM stage and pleural indentation with the GPTV3 radiomics signature to predict ALK mutation status in patients with lung adenocarcinoma." (PMID 40083024, 2025). "Univariate analysis of the effects of EGFR gene mutation and ALK gene mutation on radiological features of invasive lung adenocarcinoma." (PMID 41378298, 2025). "In a series of lung adenocarcinoma patients metastatic to the spine with mutational data for selected markers (ALK, MET, ROS1, EGFR, and KRAS), the presence of clinically targetable mutations was found to be associated with increased survival." (PMID 40647516, 2025). "Epidermal growth factor receptor (EGFR) mutations and anaplastic lymphoma kinase (ALK) rearrangements are the most common druggable targets in lung adenocarcinoma." (PMID 41378298, 2025). "In summary, GPTV3 radiomics signatures based on an SVM classifier can provide non-invasive biomarkers for predicting ALK mutation status in patients with lung adenocarcinoma." (PMID 40083024, 2025). "There is no clinical study on the relationship between three-dimensional CT imaging findings and EGFR and ALK gene rearrangements or prognosis in GGO-associated lung adenocarcinoma." (PMID 41020204, 2025). "Univariate analysis of the effects of EGFR gene mutation and ALK gene mutation on clinical features of invasive lung adenocarcinoma." (PMID 41378298, 2025). "PET/CT radiomics-based ML model provides non-invasive diagnostic method to help diagnose ALK mutation status for lung adenocarcinoma patients." (PMID 40078179, 2025). "This study aims to explore the correlation between EGFR mutation status, ALK positivity, and various demographic, radiological, and pathological features of lung adenocarcinoma." (PMID 41378298, 2025). "The present manuscript reports on an acquired ALK resistance mutation in an EML4/ALK-rearranged non–small cell adenocarcinoma of the lung." (PMID 38960389, 2025). "The radiomics-based ML model can potentially serve as a non-invasive tool to detect ALK mutation in patients with lung adenocarcinoma." (PMID 40078179, 2025). "The purpose of our study was to evaluate the performance of CT radiomics features extracted from intratumoral and peritumoral regions in predicting ALK mutation in patients with lung adenocarcinoma." (PMID 40083024, 2025). "Epidermal growth factor receptor (EGFR) and anaplastic lymphoma kinase (ALK) gene rearrangements are risk factors for the progression of lung adenocarcinoma." (PMID 41020204, 2025).
lung adenocarcinoma (continued). "Multivariate analysis was conducted to investigate the association of these parameters with EGFR gene mutation and ALK gene rearrangement in patients with GGO-associated lung adenocarcinoma." (PMID 41020204, 2025). "• The combined model based on GPTV3 radiomics features and clinical predictors effectively predicted ALK mutation in patients with lung adenocarcinoma." (PMID 40083024, 2025). "This study aimed to explore the relationship between EGFR mutations, ALK positivity, and demographic, tumor, radiological, and pathological characteristics in lung adenocarcinoma patients." (PMID 41378298, 2025). "This retrospective study aimed to investigate this association in advanced lung adenocarcinoma patients with ALK, ROS1, RET rearrangements, and EGFR mutations." (PMID 40751559, 2025). "Epidermal growth factor receptor (EGFR) mutations and anaplastic lymphoma kinase (ALK) rearrangements are common genetic alterations in lung adenocarcinoma." (PMID 41020204, 2025). "Univariable and multivariable Cox regression analysis for risk factors associated with PFS in lung adenocarcinoma with ALK-positive." (PMID 40606995, 2025). "Here, we report an advanced lung adenocarcinoma case with positive ALK rearrangement and a novel secondary mutation and its response to second-generation ALK-TKIs." (PMID 39267820, 2024). "Specialists state that lung adenocarcinoma with a signet ring morphology is often ALK-mutated, meaning that patients can benefit from ALK inhibitors." (PMID 38256374, 2024). "It aims to explore clinical, molecular, and immune microenvironment characteristics associated with PD‐L1 expression in EGFR/ALK wild‐type lung adenocarcinoma patients eligible for ICI therapy." (PMID 38396367, 2024). "This study documents the effective treatment of a patient with lung adenocarcinoma accompanied by ALK-positive mutations, who exhibited successive resistance to crizotinib, alectinib and lorlatinib." (PMID 38978737, 2024). "Highly prevalent mutations in genes such as EGFR, KRAS, and ALK contribute substantially to lung adenocarcinoma and are pivotal for recommending targeted therapies." (PMID 39323996, 2024). "The signet ring cell feature was associated with ALK rearrangement in lung adenocarcinoma; thus, these patients can benefit from tailored therapy with ALK-tyrosine kinase inhibitors (ALK-TKI)." (PMID 38256374, 2024). "This article retrospectively analyzes a case of advanced lung adenocarcinoma with the echinoderm microtubule associated protein like 4 (EML4)-ALK fusion variant 3 (V3)." (PMID 39962851, 2024). "Due to the small sample sizes for individual gene mutations, we explored the impact of pathway mutations on immunotherapy outcomes in EGFR/ALK wild‐type lung adenocarcinoma patients." (PMID 38396367, 2024). "Here, we first report a female lung adenocarcinoma patient with an acquired ALK resistance mutation (ALK 11171N) who was treated with ensartinib." (PMID 36864442, 2023). "Echinoderm microtubule-associated protein-like 4-anaplastic lymphoma kinase (ALK) fusion has been observed in 3-7% of cases of lung adenocarcinoma." (PMID 37927354, 2023). "This retrospective study evaluated all 33170 lung adenocarcinoma patients registered in the National Taiwan Cancer Registry from 2017 to 2019, of whom 9575 advanced stage patients had ALK mutation data." (PMID 37007097, 2023). "The association of smoking and ALK-TKIs on OS in treatment-naïve ALK-positive advanced lung adenocarcinoma patients is yet to be elucidated." (PMID 37007097, 2023). "An update of the GPA prognostic index including molecular markers, the Lung-molGPA, added EGFR and ALK mutation status for patients with lung adenocarcinoma." (PMID 36765679, 2023). "Some studies have shown that ALK-rearranged lung adenocarcinomas are significantly associated with the solid-predominant subtype." (PMID 36823653, 2023).
lung adenocarcinoma (continued). "In this report, we present for the first time an unreported case of lung adenocarcinoma with double ALK fusions of echinoderm microtubule-associated protein like 4 (EML4) and histone methyltransferase (SETD2), which is sensitive to alectinib." (PMID 37055606, 2023). "ALK rearrangements are found in ~7% of patients with lung adenocarcinoma and are mutually exclusive with KRAS and EGFR mutations." (PMID 36765679, 2023). "In lung adenocarcinoma, BM occurs in ~20–40% of patients with ALK rearrangements and ~25% of patients with EGFR-mutated tumors." (PMID 36765679, 2023). "Among patients with advanced stage (stages IIIB to IV) lung adenocarcinoma, 9575 had ALK mutation data; of these, 650 were ALK mutation positive with the median follow-up survival time 30.97 months." (PMID 37007097, 2023). "We report a case of typical ALK mutated lung adenocarcinoma with acquired resistance who developed an atypical second primary tumor." (PMID 36930086, 2023). "The first study found an association of ATP13A4 with high-grade serous ovarian carcinoma, while the second study linked ATP13A4 to lung adenocarcinoma through anaplastic lymphoma kinase (ALK) rearrangements." (PMID 37371498, 2023). "In this case report, we report a lung adenocarcinomas patient harboring an acquired resistance mutation ALK I1171N who showed good responses with ensartinib." (PMID 36864442, 2023). "The intergenic region (chr2: 30,193,816)-ALK fusion, which is firstly reported in lung adenocarcinoma, is a mutation with expression significance." (PMID 36755262, 2023). "We first examined the relative potency of alectinib and SHP099 in ALK+ lung adenocarcinoma cells; H3122 (ALK+ variant 1) and H2228 (ALK+ variant 3) cells were highly sensitive to alectinib, with EC50 values of 0.018 μM and 0.033 μM, respectively." (PMID 37339995, 2023). "Here, a novel rhabdomyosarcoma 2-associated transcript (RMST)-ALK rearrangement was identified in an 80-year-old Chinese man with advanced lung adenocarcinoma." (PMID 35978810, 2022). "There are no specific data about drugs management in pediatric population affected by lung adenocarcinoma and ALK mutation." (PMID 35092185, 2022). "In our previous studies, a PET/CT radiomics model was developed to predict epidermal growth factor receptor (EGFR) mutation and anaplastic lymphoma kinase (ALK) rearrangement status in lung adenocarcinoma." (PMID 35445899, 2022). "We describe the case of a 63-year-old man with a stage cIVA ALK-rearranged lung adenocarcinoma who developed a BRAF A598-T599insV mutation as a potential resistance mechanism to alectinib, a second-generation ALK TKI." (PMID 36419902, 2022). "According to research, EVs secreted from an anaplastic lymphoma kinase (ALK)-tyrosine kinase inhibitor (TKI)-resistant subclone of ALK-translocated lung adenocarcinoma cell lines can cause drug resistance in sensitive subclones." (PMID 35159299, 2022). "Herein, we report a case of lung adenocarcinoma harboring a complex ALK fusion that coexisted with a BRAF mutation, as tested by DNA-NGS prior to treatment." (PMID 36221356, 2022). "Anaplastic lymphoma kinase (ALK) gene rearrangement is a driver mutation in lung adenocarcinoma (ACA)." (PMID 35200571, 2022). "Herein, we report a 50-year-old woman with ALK-rearranged advanced lung adenocarcinoma who developed interstitial lung disease associated with alectinib therapy." (PMID 36386178, 2022). "Preoperative serum CEA levels are also associated with ALK fusion in patients with completely resected lung adenocarcinomas." (PMID 35624472, 2022). "This study will further explore the correlation between EGFR, ALK gene mutations and imaging and pathological features in invasive lung adenocarcinoma." (PMID 35340157, 2022).